SPP1 (secreted phosphoprotein 1)
Diseases named in the same sentence as SPP1 in open-access papers (continued):
Sharing a sentence is not in itself a finding about the gene and the disease.
tumor (continued). "A spatial transcriptomics analysis showed that SPP1 expression displayed significant heterogeneity in terms of spatial distribution in all samples, with focal clusters of cells expressing higher levels of SPP1 scattered throughout the tumor tissues." (PMID 39409192, 2024). "Among them, SPP1 was significantly upregulated on macrophages in ROIs with high tumor ITGB1 expression, and the expression of these two genes was significantly positively correlated by analyzing the DSP data." (PMID 39207055, 2024). "PD-L1, PD-L2, THY1, and SPP1 from tumor or immune-inhibited cells play a central role in inhibiting the function of CD8_Tpex and CD8_Tex cells during anti-tumor immunity." (PMID 38886748, 2024). "A spatial transcriptomic study identified the co-occurrence of the presence of SPP1+ Mφ in the HCC tumor area and the exclusion of CD8+ T cells from the tumor region, implying the immunosuppressive role of SPP1+ Mφ on CD8+ T cells." (PMID 39691723, 2024). "In CRC, spatial transcriptomics revealed that FAP+ fibroblasts and SPP1+ macrophages colocalized in the tumor tissues and surrounded the tumor epithelial cells, which implies that there was a potential interaction between the two." (PMID 39858416, 2024). "The polarity of CXCL9 and SPP1 in TAMs was positively associated with increased tumor infiltration of T cells, B cells, and dendritic cells (DCs), although CXCL9 positivity was associated with better prognostic value compared to SPP1." (PMID 38542388, 2024). "It has also been demonstrated that macrophages expressing TREM1 are important in the progression of HPV+ OPSCC and that fibroblasts with a matrix-CAF phenotype collaborate with SPP1-expressing TAMs to promote tumour progression in HNSCC." (PMID 38803348, 2024). "In contrast, SPP1+macrophages predominantly utilize glycolysis, a process that propels tumor metastasis by stimulating angiogenesis and matrix remodeling." (PMID 38185636, 2024). "IL-1-activated CRC EGCs via IL-6, in turn, directly promote the differentiation of tumor-infiltrating monocytes towards SPP1+ TAMs." (PMID 39030280, 2024). "These animals are a valuable addition to help reveal the role and fate of SPP1+ TAM during tumour progression." (PMID 39430099, 2024). "In a recent study, the collaborative actions of CXCL9 and SPP1 (CXCL9:SPP1) were found to collectively dictate the polarity of tumor-associated macrophages (TAMs) within the TME, exerting profound effects on tumor progression and treatment responses." (PMID 38217023, 2024). "Our analysis identified the SPP1 pathway as the primary interaction between tumor and immune clusters." (PMID 39505867, 2024). "Specifically, SPP1 released from tumor cells interacted with CD44, ITGAV, ITGA5, ITGB1, and ITGB5 on immune clusters." (PMID 39505867, 2024). "Secreted phosphoprotein 1 (SPP1), an extracellular glycoprotein with phosphorylated residues, exhibits a close association with various aspects of tumor biology, notably proliferation, migration, and invasion, particularly in the context of LUAD." (PMID 38622716, 2024). "We found that the macrophage chemotactic factor SPP1, which is one of the largest secreted proteins in the tumour microenvironment and can be upregulated by the ERK/JUN signalling pathway 37, was significantly upregulated in MES-like GBM cells." (PMID 39629136, 2024). "In HNSCC, TAMs expressing SPP1 give rise to a pro-angiogenic SPP1+CCL18+ TAM subset, implicated in tumor growth and metastasis." (PMID 39286635, 2024). "Here, we identified SPP1 as the critical secretion factor for the process by which tumor B4GALNT1 modulates the recruitment or polarization of macrophages and Th2 cells." (PMID 39616302, 2024). "Functionally, it was determined that SPP1+ macrophages exert an immunosuppressive role, while CD14+ monocytes were implicated in promoting tumor progression and angiogenesis." (PMID 38600248, 2024).
tumor (continued). "In mouse tumor models, blockade or macrophage-specific knockout of SPP1 can destroy the TIB structure and enhance the efficacy of anti-PD-1 therapy." (PMID 39085965, 2024). "One study analyzed 144,878 cells from 14 pairs of iCCA tumor and non-tumor liver tissues using single-cell RNA sequencing and found differential expression of S100P and SPP1 in iCCA portal macrotubules (iCCAphl) and peripheral microtubules (iCCApps)." (PMID 39290697, 2024). "In tumor tissues, SPP1 + macrophages possessed the highest proportion of tdTompos cell, suggesting that these tumoral SPP1 + macrophages had the strongest phagocytic ability." (PMID 39696410, 2024). "We observed that ICC tumor cells exhibited enhanced proliferation ability when stimulated with SPP1 protein and in the presence of fetal serum (mimicking the condition of tumor cells near blood vessels)." (PMID 39716897, 2024). "An interesting discovery is that specific reciprocal communication occurs between POSTN+ fibroblasts and SPP1+ macrophages, with an upward trend in the interaction strength during tumor progression." (PMID 38519500, 2024). "The analysis of scRNA-seq data showed that SPP1 was highly expressed in malignant cells and HPC-like cells and mainly involved in the interaction among tumor-associated macrophage, T cells, and malignant cells via SPP1–CD44 and SPP1–(ITGA5 + ITGB1)." (PMID 38282028, 2024). "SPP1 can influence the immune regulation, cell survival, tumor progression and prognosis by affecting the tumor immunological microenvironment." (PMID 38706319, 2024). "Based on these results, we further focused on POSTN+ fibroblasts and SPP1+ macrophages and investigated how they interact with each other and how their cellular communication regulates tumor cells." (PMID 38519500, 2024). "The qRT-PCR results also suggested that overexpression of TRPM2-AS inhibited miR-497-5p and promoted the expression of SPP1 in tumor of nude mice." (PMID 38956502, 2024). "It has also been suggested that SPP1 was correlated with poor clinical outcomes and promote tumor progression by interacting with carcinogenic genes and facilitating immune cell infiltration." (PMID 38336764, 2024). "We compared macrophage profiles to the obtained landscape profiles and found that SPP1-expressing macrophages became dominant in moderately differentiated and invasive tumor regions, which is consistent with previous studies." (PMID 39639005, 2024). "Accumulated evidence revealed that LAMs shared a high expression of typical genes (such as APOE, APOC1, GPNMB, TREM2, SPP1 etc.)and played a central role in tumor immunity." (PMID 38346944, 2024). "SPP1 was sufficient to induce fibroblast reprogramming and neutralizing antibodies against SPP1-blocked fibroblast activation induced by tumor cells." (PMID 39335478, 2024). "This cascade increases SPP1 expression, facilitating the binding of transglutaminase to the extracellular matrix, thereby mediating tumor cell adhesion and fostering malignant biological activity." (PMID 39610830, 2024). "Previous studies have suggested that tumor cells play a vital role in the formation of SPP1 + macrophages." (PMID 39696410, 2024). "It is formed by the interaction of SPP1 + macrophages and CAFs from immunotherapy-naïve patients, and this structure limits the infiltration of immune cells into the tumor core." (PMID 38856921, 2024). "The scRNA-seq results revealed that myeloid cells were heterogeneous and strongly correlated with tumor cells in the TIME in HNSCC and identified tumor-specific SPP1 + Macs, which were positively correlated with poor prognosis of HNSCC patients." (PMID 39726047, 2024). "Studies have identified the SPP1 pathway as a crucial mediator of interaction between TAMs and tumor epithelial cells, and between TAMs themselves." (PMID 39776914, 2024).
tumor (continued). "For example, TGFB3-SDC4 and INHBA-TGFBR3 were found between POSTN+ fibroblasts and tumor cells and CXCL5-BDKRB2 and CCL7-ACKR2 were found between SPP1+ macrophages and tumor cells." (PMID 38519500, 2024). "Evidence shows that secreted phosphoprotein-1 (SPP1) is highly expressed in a variety of tumor types, which promotes tumor proliferation, invasion, and tumor stemness." (PMID 39555078, 2024). "C1QC+TAMs mostly receive CSF, CXCL, and MIF signals from CAFs, while SPP1+TAMs can communicate with CAFs through the pro-tumor FN1 or VEGF pathways." (PMID 39323622, 2024). "Remarkably, the interactions involving SPP1 were significantly enriched in primary tumours with bone metastases." (PMID 38445456, 2024). "The coexistence of tumor-specific SPP1+ TAMs and CAFs has been identified at the tumor boundary in the TIME of CRC and HCC." (PMID 39107856, 2024). "used scRNA‐seq and ST to identify and orthogonally validate a tumor‐associated FAP1+ fibroblasts and SPP1+ macrophages in CRC, a mechanism involving chemerin, TGF‐β and IL‐1 to form immune‐resistant cellular niches with impaired T cell functioning." (PMID 39376738, 2024). "It was found that SPP1 expression was correlated with 4 tumor-infiltrating immune cells by utilizing the TIMER database." (PMID 38329443, 2024). "Further analyses reveal a positive correlation between ITGB1high tumor cell counts and SPP1+ macrophage density, as well as the spatial proximity of these two cell types." (PMID 39207055, 2024). "Several studies have confirmed that osteopontin (also known as SPP1, OPN), a protein encoded by the Spp1 gene, can activate the MAPK signaling pathway to play a role in tumor progression, inflammatory responses, and neuroprotection." (PMID 38731915, 2024). "With regard to myeloid cells, the liver-resident macrophages and inflammatory monocyte/macrophages were markedly replaced by tumor-associated macrophages (TAMs), with TREM2+ and UBE2C+ TAMs enriched in PTs, while SPP1+ and WDR45B+ TAMs in MTs." (PMID 38414027, 2024). "It is believed that SPP1+ Mac promotes tumor growth through mechanisms such as immune suppression, epithelial-mesenchymal transition, angiogenesis, and remodeling of the matrix of CAFs." (PMID 38755647, 2024). "SPP1+VEGFA+ TAM were also trending towards increased proportions in tumor samples (Diff = 3.4%, p-value = 0.21)." (PMID 39075108, 2024). "INHBA on SPP1+ macrophages is predicted to interact with ACVR1 on tumor cells, targeting downstream genes, including SERPINE1 and SMAD3, which positively regulate cyclin-dependent protein kinase activity." (PMID 38519500, 2024). "Together, these evidences indicated that the SPP1+ macrophage infiltration in LI+ cells accelerated LI, in turn pDCS infiltration in LI- cells, modulated anti-tumor immunity." (PMID 38632387, 2024). "High expression of SPP1 correlates with a worse clinical outcome in several cancer types and accordingly SPP1+ macrophages are thought to support tumour progression as tumorigenic macrophages." (PMID 39430099, 2024). "Specifically, this investigation systematically investigates the impact of SPP1 on tumor progression, prognosis, and immune in individuals diagnosed with LUAD." (PMID 38329443, 2024). "CDKN2A, BIRC5, and SPP1 expression levels were significantly upregulated in tumor tissues (p < 0.001), while IGF1 expression was considerably downregulated (p < 0.001)." (PMID 39042294, 2024). "The shorter spatial distance between SPP1 + SIRPα + macrophages and both tumor cells and CD8 + T cells enables their close crosstalk." (PMID 39696410, 2024). "To explore the expression of SPP1 in tumor tissues, we performed differential analysis of SPP1 in tumors and normal tissues and found significant differences in 18 cancer types in all TCGA data." (PMID 38648200, 2024).
tumor (continued). "Because the infiltration and interaction of POSTN+ fibroblasts and SPP1+ macrophages were greatest in the A stage, we then analyzed the ligand‒receptor (LR) interaction between these two cell types and tumor cells." (PMID 38519500, 2024). "The tumor area activated various proliferation and metastasis-related signaling pathways (such as MK, SPP1, SEMA3, MIF, and VEGF) and immunosuppression-related signaling pathway (GALECTIN)." (PMID 39505867, 2024). "Simultaneously, SPP1 downregulated CD40LG, TNFSF15, TNFRSF13B, IL6R, KLRK1, and other immune stimulants, indicating that SPP1 played a role in the evasion of tumor immunity by controlling the immunosuppressive surroundings." (PMID 38329443, 2024). "Studies have reported that SPP1 can activate the PI3K/AKT/mTOR signaling pathway through PKCα phosphorylation, a pathway closely associated with tumor invasion and metastasis." (PMID 39066845, 2024). "In line with the results of the cell experiments, the results of our subcutaneous coinjection tumor model in nude mice confirmed the role of SPP1 in macrophages in tumorigenesis and the suppressive effect of SPP1 knockdown in macrophages on tumors." (PMID 39726047, 2024). "In a separate study on colorectal cancer (CRC), SPP1 + TAMs were also recognized as a tumor-promoting subset." (PMID 38443595, 2024). "To validate the phagocytic ability of SPP1 + macrophages in vivo, we reanalyzed scRNA-seq data from a previously published mouse tumor model." (PMID 39696410, 2024). "SPP1 is an important extracellular matrix component secreted by a variety of cells, including tumour cells, immune cells, fibroblasts, osteoblasts, smooth muscle cells, lymphocytes and epithelial cells." (PMID 38886539, 2024). "Our analysis using the HNSCC dataset of TCGA database revealed significantly elevated expression of MMP1, MMP3, MMP12, and SPP1 in tumor tissues compared to normal tissues." (PMID 39596132, 2024). "Blockade of SPP1 with an RNA aptamer strongly inhibited tumor growth and tumor infiltration by CD206+ and F4/80+ macrophages in xenograft mouse models." (PMID 39516356, 2024). "The overlap of target gene enriched pathways included cell-substrate junction assembly, ECM-receptor interaction, and osteoblast differentiation, suggesting the combined oncogenic effects of POSTN+ fibroblasts and SPP1+ macrophages on tumor cells." (PMID 38519500, 2024). "Among the interaction molecular pairs, tumour invasion‐related pairs, including CD74_MIF, SPP1_CD44, were enriched among macrophages and MYH11+ CAFs." (PMID 39294858, 2024). "Among them, Macro-2 seems to be a key player in the tumor metastatic cascade, characterized by expression of SPP1, CCL18, CXCL5, CCL2, and CCL7." (PMID 38281962, 2024). "In this study, we demonstrated the crucial role of the cascade reaction among tumor-derived SPP1, lung epithelial cells and neutrophils in the formation of the PMN and HCC lung metastasis." (PMID 39529085, 2024). "Compared with those in adjacent tissues, the expression levels of CDKN2A, BIRC5, and SPP1 were significantly upregulated in tumor tissues (p < 0.05), while the expression of IGF1 was considerably downregulated (p < 0.001)." (PMID 39042294, 2024). "Recent studies have indicated SPP1 in cancers as a marker of pro-tumor macrophages and cancer cells, leading to worse prognosis for patients." (PMID 39075108, 2024). "Beyond SPP1+ macrophages, other myeloid cell subtypes have emerged as critical players at the tumour border." (PMID 39350478, 2024). "A similar study observed the colocalisation of cancer stem cells and SPP1+ macrophages in the hypoxic regions at the tumour boundary." (PMID 39350478, 2024). "SPP1 has been confirmed as an effective molecule promoting tumor progression and metastasis in various cancers." (PMID 39529085, 2024). "This study provided evidence that the upregulation of SPP1 exacerbates the prognosis of CRC patients by facilitating tumor evasion from immune responses." (PMID 38397058, 2024).
tumor (continued). "Tumor-derived SPP1 engenders mesenchymal stem cells (MSCs)-to-CAFs transformation in the TME to promote tumor growth and metastasis via the SPP1-MZF1-TGFB1 pathway." (PMID 39335478, 2024). "As expected, MMP1, MMP3, MMP12, and SPP1 displayed significantly higher expression in tumor tissues compared to normal samples." (PMID 39596132, 2024). "Our study also reveals that SPP1 is highly expressed in tumor tissues and cell lines of EC, and overexpression of SPP1 significantly promote angiogenesis in EC." (PMID 38956502, 2024). "RNA-seq data revealed higher SPP1 expression (p = 0.0008) in tumor tissues over adjacent normal compartments." (PMID 39409192, 2024). "The immune genes CXCL1, CXCL2, IL1B, IL6, CXCL8, PTGS2, and SPP1 demonstrated elevated expression levels in tumor tissue (TU) relative to all other tissues, thus validating the results obtained from the NanoString analysis (Supplementary 1)." (PMID 38979413, 2024). "We investigated the expression pattern of ERα, ERRα and SPP1 in the tumor tissues of both GCRsim exposed and control mice." (PMID 39682141, 2024). "In line, we identified a strong directional flow from tumor-infiltrating monocytes towards intermediate macrophages, which in turn further branched into two opposite paths, ending either in SPP1+ TAMs or C1Q+ TAMs." (PMID 39030280, 2024). "Among nonmalignant cell types, RSPO1+ fibroblasts and FOLR2+ macrophages were identified as potential tumor-suppressing populations and POSTN+ fibroblasts and SPP1+ macrophages were identified as tumor-promoting populations." (PMID 38519500, 2024). "Tumor angiogenesis, cell migration, extracellular-matrix receptor interaction, and tumor vasculature pathways are enriched in SPP1+ Mph, whereas complement activation and antigen processing and presentation pathways are enriched in C1q+ Mph." (PMID 38500875, 2024). "In our study, four macrophage subsets were identified in primary tumor and metastatic specimens: SPP1+ macrophages, C1QC+ macrophages, CXCL10+ macrophages and FOLR2+ macrophages." (PMID 38519500, 2024). "Considering that SPP1 can be secreted by various matrix cells in the tumor microenvironment, we detected SPP1 expression via RNAscope In Situ Hybridization and demonstrated that the tumorous secretion of SPP1 was dominant." (PMID 39529085, 2024). "SPP1-expressing TAM subpopulations have been shown to promote intravasation and metastasis in HNSCC and low TAM containing tumours (CD68 CD163) have been associated with better survival." (PMID 38803348, 2024). "As a result, the functional status and the phenotype of SPP1 + SIRPα + macrophages are possibly influenced by the tumor cells." (PMID 39696410, 2024). "According to recent studies, SPP1 + Macs function as Angio-TAMs or Inflam-TAMs, which promote malignant tumor progression in diverse cancer types." (PMID 39726047, 2024). "Given that SPP1+macrophages are associated with poorer clinical outcomes in cancers 32 and PDPN is related to tumor relapse 33, these two subsets were annotated as TAMs." (PMID 39239507, 2024). "Conversely, the SPP1 expression was found to be downregulated in certain tumor types, such as KICH and KIRC." (PMID 39727934, 2024). "In conclusion, we revealed that SPP1+ macrophages and CD14+ monocytes were highly associated with immunosuppressive TME and tumor angiogenesis, respectively." (PMID 38600248, 2024). "In this study, we applied single-cell RNA sequencing (scRNA-seq) analyses of paired tumor and normal tissues from 5 HNSCC patients to identify tumor-specific SPP1 + Macs." (PMID 39726047, 2024). "Like those in POSTN+ fibroblasts, the number of SPP1+ macrophages in tumor tissues were dramatically increased, and higher infiltration correlated with a shorter overall survival in TCGA HNSCC patients." (PMID 38519500, 2024). "Then tumor cells labeled with CFSE were co-cultured with THP-1-derived SPP1 + macrophages for 4 h in serum-free medium." (PMID 39696410, 2024).